INS (insulin)
Diseases named in the same sentence as INS in open-access papers (continued):
Sharing a sentence is not in itself a finding about the gene and the disease.
cancer (continued). "Patients treated with insulin for a long period of time have a higher risk of cancer, and with the increasing duration of insulin treatment, the incidence of cancer may increase." (PMID 25329503, 2014). "Since both insulin and IGF1 pathways share cognate receptors, insufficient insulin action may cause dysregulation of the IGF1-SREBP-HMGCR-mevalonate-Ras pathway to increase cancer risk." (PMID 24886453, 2014). "Moreover, genes in the differential network, particularly those involved in the pathways such as mTOR, insulin, and apoptotic signaling, showed association with cancer." (PMID 25057922, 2014). "We found that those who have used ADM, particularly metformin, for 1–4 years as well as those who started insulin use within 0–3 years after the initiation of oral anti-diabetic medication might be at higher risk of cancer." (PMID 25419576, 2014). "Other hormonal adaptations associated with fat loss, improved insulin sensitivity, and reduced cancer risk include increased serum steroid hormone binding globulin and reduced levels of free estrogens and testosterone, and increased serum IGFBP-1 and reduced free IGF-1 concentrations." (PMID 24628815, 2014). "Risk of cancer may be directly related to the dose of insulin (analogs) and/or effects on metabolic control." (PMID 24904529, 2014). "On the contrary, sulfonylurea drugs or insulin are associated with increased cancer risks." (PMID 24884617, 2014). "Although insulin has been associated with a variety of cancers and liver cell functions, and ROS as secondary messengers mediate the cancers signals, it remains unknown whether ROS participate in transmitting insulin signaling." (PMID 24895527, 2014). "Thus, rapid progression from the initiation of OADM to the requirement for insulin treatment can be a sign of a worsening health status and can be seen as a potential risk factor for cancer." (PMID 25419576, 2014). "It is well known that high level of insulin is a significant risk factor for cancer." (PMID 25580464, 2014). "Highly controversial epidemiological studies suggested that therapeutic use of the insulin analog insulin glargine was associated with an increased risk for development of cancer, but the ORIGIN trial recently provided strong evidence that this is not the case." (PMID 24260289, 2013). "From a clinical perspective, it is important to establish whether insulin concentrations are sufficient to induce a higher risk of cancer." (PMID 24348585, 2013). "Interestingly, preliminary data demonstrate that a low carbohydrate insulin-inhibiting diet, associated with ketosis, is safe and correlated with stable disease or partial remission in patients with advanced cancer." (PMID 24073332, 2013). "Our study highlights previously unknown PKM2-mediated effects of insulin in promotion of cancer metabolism, which probably explains the observations of increased cancer risk under hyperinsulinemic condition." (PMID 23837608, 2013). "For calcium absorption, it is believed that a level of 80 nmol/L or higher is optimal, whereas for fracture risk, falls, cancer, insulin sensitivity and potentially immune function, levels as high as 120 nmol/L may be necessary." (PMID 23875738, 2013). "Thus, treatment strategies, including weight-loss, physical activity, and insulin-lowering medications are logical strategies to reduce insulin secretion, C-peptide and future cancer risk." (PMID 23405181, 2013). "Sulfonylurea and insulin therapy were found to be mildly associated with increased overall cancers." (PMID 23401790, 2013). "In essence, the impact of insulin on cancer risk may be large because of its capacity to deliver a more mitogenic, IGF-like signal either through isoform A of the insulin receptor or through insulin receptor: type I IGF receptor hybrids." (PMID 23983688, 2013). "Indeed several trials documented that use of insulin secretagogues particularly sulfonylureas, is associated with higher cancer incidence and mortality." (PMID 23476808, 2013).
cancer (continued). "Recent epidemiological studies have suggested that some insulin analogues could be associated with an increased risk of cancer." (PMID 24131755, 2013). "The increase in percentage point of HbA1c was associated with 26% increase in risk of cancer (HR 1.26; 95% CI; 1.03–1.55), and use of insulin was associated with markedly lower cancer risk with multivariable HR 0.17 (95% CI; 0.09–0.32) in insulin-users group as comparing to noninsulin group." (PMID 23476808, 2013). "Therapeutic insulin has been shown to increase cancer risk in numerous studies." (PMID 23983688, 2013). "The negative energy balance may be an important factor in lowering the susceptibility to cancer because of direct or indirect effects on levels of insulin, insulin-like growth factor-I (IGF-I), and inflammatory biomarkers." (PMID 24073332, 2013). "Therefore, the authors suggested that the relation between higher cancer risk and human insulin use were most likely to be due to confounding and/or surveillance bias rather than causal." (PMID 23308218, 2013). "PI3K-dependence of PKM2 expression supports the notion that PI3K pathway is central to insulin signalling in cancer cells and correlates with high frequency of PI3K mutations in several cancer types, which may lead to increased expression of PKM2." (PMID 23837608, 2013). "This possibly explains the link between high insulin levels and elevated cancer risk." (PMID 23837608, 2013). "Another mechanism by which insulin could increase the risk of cancer in obese individuals with hyperinsulinaemia is by direct stimulation of type I IGF receptor." (PMID 23983688, 2013). "Whether insulin treatment increases risk of cancer is an important issue because almost all patients with DM will eventually require insulin treatment." (PMID 24282613, 2013). "This phenomenon, known as reverse causation, could also be present for other forms of cancer, which can impair glucose control via several mechanisms, leading to an overestimation of the actual risk associated with insulin therapy." (PMID 23209929, 2012). "Increased circulating insulin level may be another explanation for the increased cancer risk associated with sulfonylureas and insulin therapy." (PMID 22778714, 2012). "Cancer risk increases by an estimated 20% for each year of insulin therapy." (PMID 22778714, 2012). "Furthermore, metformin has been associated with a lower risk of CVD, total mortality and cancer incidence compared with sulfonylureas and insulin." (PMID 22719972, 2012). "However, a wide variability of estimates can be observed even within a specific cancer type; for example, for colorectal cancer, the risk associated with insulin therapy ranges from 1.02 to 2.10." (PMID 23209929, 2012). "Insulin can act as a mitogen and is associated with several cancers." (PMID 23304125, 2012). "However, it is possible that some of these molecules differ from human insulin in some respect, thus producing undesired effects, including a higher risk for cancer." (PMID 23209929, 2012). "Whether Triptolide can be targeted to insulin resistant patients with higher risk for cancer development might be a potential line of research." (PMID 23226522, 2012). "The cause for the increased risk of cancer in type II DM patients is not clearly understood but may be related to dietary-induced elevated insulin and elevated insulin-like growth factor-I levels." (PMID 22421948, 2012). "In fact, it is possible that insulin therapy is diversely associated with different cancer types." (PMID 23209929, 2012).
cancer (continued). "Interestingly, among studies which assessed overall cancer incidence or cancer-related mortality, those providing higher estimates of risk with insulin therapy adjusted for a small number of confounders." (PMID 23209929, 2012). "Insulin signalling pathway is involved in the pathogenesis of various malignancies, increase cancer risk through its effect on cell proliferation, differentiation and apoptosis, and was reported to be involved in the tumorigenesis and neoplastic growth of the prostate." (PMID 22830977, 2012). "As a consequence, the administration of exogenous insulin or insulin-mimetic compounds to type 2 diabetic patients might hyperactivate IR-driven mitogenic signaling, increasing the overall cancer risk in these patients." (PMID 22203527, 2011). "Insulin may also potentially increase the risk of cancer through growth promoting and anabolic effects mediated by binding to the type 1 insulin-like growth factor (IGF) receptor." (PMID 21410860, 2011). "Insulin can act as a mitogen and has been associated with several cancers." (PMID 21696633, 2011). "Second, obesity causes hormonal changes such as insulinemia and insulin promotes cancer." (PMID 22267462, 2011). "In contrast, a UK study found that despite a higher risk of overall cancer among diabetic patients receiving insulin or sulfonylurea compared to those using metformin, the risk was similar for different insulin formulations at the doses used in clinical practice." (PMID 21738645, 2011). "Sulfonylurea (SFU) use, like insulin, has been implicated in cancer risk." (PMID 21773024, 2011). "In this study, we examined whether cancer incidence was associated with the use of insulin glargine compared to intermediate/long-acting human insulin (HI) using the Taiwan National Health Insurance claims database." (PMID 21738645, 2011). "More recently, metformin has been associated with decreased cancer incidence and mortality in diabetic patients and the insulin-lowering effects of metformin may be integral to its anticancer properties." (PMID 21470407, 2011). "In addition, it is becoming clear that there are insulin-independent mechanisms of glucose action on cancer risk, particularly through energy-sensing pathways and glucotoxic damage." (PMID 20182531, 2010). "Multivariate adjustment has shown that the sulfonylurea cohort had greater cancer-related mortality compared with the metformin cohort (1.3 (95% CI 1.1-1.6); p = 0.012), whereas insulin use was associated with an adjusted cancer-related mortality of 1.9 (1.5 - 2.4; p < 0.0001)." (PMID 21084729, 2010). "A manuscript apparently containing the first description of an increased cancer risk in diabetic patients taking glargine insulin was submitted to Diabetologia which was eventually sent to six reviewers, three of whom recommended that the paper be rejected [Smith and Gale, 2009]." (PMID 24966880, 2009). "A comprehensive review of insulin and cancer risk is beyond the scope of this report." (PMID 18665244, 2008). "The mechanisms by which these factors increase cancer risk have been hypothesized to involve insulin and the insulin-like growth factor axis, which are intimately involved in glucose and energy homeostasis." (PMID 17533398, 2007). "Greater exposure to mitogenic factors, such as growth hormone, insulin, insulin-like growth factors, and sex steroids, could also result in increased cancer risk." (PMID 12671701, 2003). "Surgery was associated with a lower rate of female-specific cancers in the two highest thirds (HRadj = 0.48; 95% CI [0.33, 0.72]; p < 0.001, and HRadj = 0.49; 95% CI [0.34, 0.70]; p < 0.001) with evidence of heterogeneity by insulin level (adjusted treatment–insulin interaction p = 0.021)." (PMID 41490246, 2026).
cancer (continued). "Importantly, subgroup analyses showed that the associations between surgery and female-specific cancer incidence, as well as female-specific cancer-related mortality, were stronger in women with high baseline insulin levels (insulin-treatment interaction p = 0.021 and 0.039, respectively)." (PMID 41490246, 2026). "GLP-1 RA treatment was associated with a significant reduction in the risk of 10 cancers, including esophageal, colorectal, endometrial, gallbladder, kidney, liver, ovarian, and pancreatic cancers, as well as meningioma and multiple myeloma, compared to insulin-treated patients." (PMID 39796190, 2025). "In addition,the role of 5-aminovaleric acid as a precursor of 5-aminovaleric acidbetaine, which is a compound associated with the gut microbiota withpositive health effects such as fetal brain development, insulin secretion,and reduced cancer risk, has been studied." (PMID 40705851, 2025). "While it hasn’t been explored specifically in relation to cancer, enhancing the insulin sensitivity of adipose tissue through exercise might reduce the heightened rate of fat breakdown linked to cancer, potentially safeguarding against muscle and tissue loss associated with cancer cachexia." (PMID 40487761, 2025). "Additionally, unhealthy dietary patterns may have an impact on the physiological homeostasis of glucose and insulin, which may increase cancer risk." (PMID 39018497, 2025). "In addition, the effects of adiposity distribution on circulating molecular traits—such as sex hormones, inflammatory biomarkers, and metabolic features, including those related to insulin signaling and fatty acid metabolism—in relation to cancer risk are also understudied." (PMID 40987470, 2025). "Studies have demonstrated that adults with high body fatness and elevated insulin levels tend to have abnormal serum concentrations of adipokines, with reduced adiponectin and elevated leptin levels, which have been associated with increased risk for adiposity-related cancers." (PMID 39317703, 2024). "Indeed, excessive adipose tissue is associated with higher levels of insulin, which may enhance the proliferation of cancer cells." (PMID 38892682, 2024). "However, there may be other mechanisms through which alcohol consumption can reduce cancer risk, such as increased insulin sensitivity through increased lipocalin levels." (PMID 38233852, 2024). "In addition, skeletal muscles may be associated with insulin growth factor signaling, host immunity, systematic inflammation, and hormonal activity, which are related to poor cancer prognosis." (PMID 36831420, 2023). "Metformin may reduce the risk of cancer by 30 to 50% when compared to insulin or sulfonylureas." (PMID 36830690, 2023). "Studies have also suggested that higher DED scores are linked to lower dietary antioxidant intake and higher insulin concentrations, which may increase the risk of cancer/tumor growth by inhibiting apoptosis, stimulating cell proliferation, and enhancing angiogenesis." (PMID 36879242, 2023). "Via its action as an insulin-sensitizer, metformin has also proven useful to treat PCOS, and data, albeit controversial, indicates benefits in reducing the risk of some cancers; the latter may also depend on its actions as an insulin sensitizer and enhancing glucose utilization." (PMID 35909294, 2023). "Therefore, it is hypothesized that genetic variation affecting the IGF1/insulin axis may also influence cancer risk, progression and therapy response." (PMID 38136416, 2023). "A high concentration of anti-nutrients has an adverse effect but may exert beneficial health effects at adequate amounts by reducing blood glucose levels and the insulin response to starchy foods and/or plasma cholesterol and triglyceride to reduce cancer risk." (PMID 36235722, 2022).
cancer (continued). "Similar but lower levels of chronic tissue damage from everyday exposures may release peripheral serotonin and contribute to multiple clinical FA phenotypes including thyroid dysfunction, immune dysregulation, dyslipidemia, insulin sensitivity, abnormal BMI, and cancer susceptibility." (PMID 35454946, 2022). "The fly studies suggest that insulin resistance caused by ImpL2 may play a role in cancer cachexia." (PMID 35319749, 2022). "For example, people who often consume rich saturated fat and refined sugar in their daily life might increase body fat accumulation and impaired glucose and insulin regulation, which in turn altered physiological hormonal homeostasis and ultimately increased cancer risk." (PMID 36714554, 2022). "Whether fasting insulin (FI) plays a role in cancer risk remains unclear." (PMID 35530326, 2022). "Interestingly, several short-term randomized clinical trials have indicated promising effects of alternate day fasting or a 5:2 diet in improving some cancer risk factors, including decreased fasting glucose, insulin, and leptin levels and increased adiponectin." (PMID 35984550, 2022). "In addition, the current study also suggests that insulin, thyroid hormone, and cancer-associated microRNAs may be potential therapeutic targets that should be explored by basic science studies to improve the function of the RV to match that of the LV." (PMID 36552341, 2022). "In addition, it has been reported that severely malnourished or weight-loss patients with cancer have decreased insulin levels, and oral and intravenous glucose stimulation induces abnormally low insulin secretion, which correlates with the degree of weight loss." (PMID 35752767, 2022). "Increased risk of various cancers onset in obese patients may be partly associated with the enhanced secretion of endogenous hormones and steroids (e.g., sex hormones and insulin) and the subsequent disturbed balance between cell proliferation, differentiation and apoptosis." (PMID 35328822, 2022). "Elevated insulin levels may also be associated with cancer progression." (PMID 35984550, 2022). "Thus, it is clear that each compound of insulin, sulfonylureas and thiazolidinedione group could be assessed for risk of various types of cancer before its use as antidiabetic or anticancer medication." (PMID 34535145, 2021). "Furthermore, it wasshown that insulin can cause drug resistance in differenttypes of cancer." (PMID 34308576, 2021). "Results of other studies have suggested that, among glucose-lowering medications, insulin and sulfonylureas, drugs that increase insulin secretion, may increase the cancer risk through the interaction with insulin and IGF-1 receptors, leading to stimulation of cell proliferation." (PMID 34441749, 2021). "First of all, hyperinsulinemia is a hallmark of IR, and it is well established that insulin contributes to cancer development by stimulating pro-mitogenic, angiogenic, and anti-apoptotic effects, mainly through binding to insulin receptor A, which is expressed in cancer cells." (PMID 34830295, 2021). "The cause of reduced skeletal muscle glucose uptake in cancer is incompletely defined but was observed with a concurrent decrease in insulin-stimulated microvascular perfusion of muscle in tumor-bearing mice, which is similar to what has been observed in insulin-resistant obese subjects." (PMID 33801684, 2021).